MUC5AC (mucin 5AC, oligomeric mucus/gel-forming)
Diseases named in the same sentence as MUC5AC in open-access papers (continued):
Sharing a sentence is not in itself a finding about the gene and the disease.
gastrointestinal tumors (6 papers, 2014 to 2025). "As the principal gastrointestinal mucins capable of forming viscous gels, MUC2 and MUC5AC can similarly play important roles in the pathogenesis and resilience of other mucin-secreting gastrointestinal tumors." (PMID 26436698, 2015). "Similarly, mucinous differentiation of gastrointestinal tumors, in particular increased or de novo expression of MUC2 and/or MUC5AC, is widely believed to imply an adverse clinicopathological feature." (PMID 26436698, 2015). "The results of RT-PCR using 30 gastrointestinal tumor cell lines and an RNA panel from systemic normal tissues suggested that Gli is necessary but not sufficient for MUC5AC expression, which was consistent with the results from immunohistochemistry of clinical specimens." (PMID 25166306, 2014).
colonic polyps (3 papers, 2006 to 2023). "Numerous groups have reported varying percentages for MUC5AC expression amongst different subtypes of colonic polyps." (PMID 36900282, 2023).
MUC5AC also shares sentences with these, for which no sentence is quoted: idiopathic pulmonary fibrosis (5 papers); lung (5); colorectal adenocarcinoma (3); non-small cell lung carcinoma (3); papillary adenocarcinoma (3); acinar cell carcinoma (2); bladder cancer (2); chronic gastritis (2); hyperplastic polyp (2); Pancreatic cysts (2); primary angle-closure glaucoma (2); pseudomyxoma peritonei (2); respiratory infections (2); tubulovillous adenoma (2); ulcer (2); acalculous cholecystitis (1); acinar cell carcinoma of the pancreas (1); acute lymphoblastic leukemia (1); acute respiratory distress syndrome (1); appendiceal adenocarcinomas (1); Atrophy (1); autoimmune disease (1); benign neoplasm (1); bladder adenocarcinoma (1); breast adenocarcinoma (1); bronchioalveolar carcinoma (1); bronchioloalveolar carcinoma (1); cardiovascular disease (1); cecum cancer (1); Chagas disease (1).
A further 68 diseases each share a sentence with MUC5AC in 1 paper.